IL10 (interleukin 10)
Diseases named in the same sentence as IL10 in open-access papers (continued):
Sharing a sentence is not in itself a finding about the gene and the disease.
COVID-19 (continued). "The nuanced understanding of cytokine interactions, including the pleiotropic effects of cytokines like IL10, supports our conclusion of the treatment’s net anti-inflammatory effect, contributing to its efficacy in managing COVID-19-related inflammation." (PMID 38543303, 2024). "The clinical significance of the increased IL-10 levels in COVID-19 patients has been interpreted as an immune-inhibitory negative feedback tool triggered by the rapidly increasing pro-inflammatory mediators and an attempt to prevent tissue damage." (PMID 39345212, 2024). "We found increased levels of respiratory IL-6 and IL-10 in patients with more severe COVID-19 compared to less severe patients." (PMID 39633683, 2024). "For instance, genotyping of cytokine-related single-nucleotide polymorphisms (SNPs), e.g., IL-6 rs1800796, IL-10 rs1800896, TNF-α rs1800629, and IFITM3 rs12252, has shown them to underlie the differential viral virulence and severity of COVID-19." (PMID 38400050, 2024). "The z score was also higher for IL-10, with IL-10 elevated in severe COVID-19, but also able to suppress hyper-cytokinemia." (PMID 39531435, 2024). "Numerous studies have demonstrated that IL-10 and IL-6 are important factors for predicting the exacerbation of COVID-19 and are significantly positively correlated with the severity of disease and the mortality rate of patients with COVID-1912,46,47." (PMID 38710800, 2024). "This is consistent with recent findings that highlight IL-10’s role in balancing the immune response in severe COVID-19 cases." (PMID 39203987, 2024). "Using the residual nasopharyngeal swab samples, our study demonstrates the significant association between respiratory immune mediators (including IL-10, IL-6, MCP-1, and MCP-3) and COVID-19 severity." (PMID 39633683, 2024). "Several studies have shown that levels of IL-10 result in poor disease progression in patients with COVID-19." (PMID 38707035, 2024). "The drastic initial rise of IL-10 in COVID-19 severe patients is a very much distinguishing and seemingly paradoxical observation in contrast to its classical anti-inflammatory role." (PMID 38707035, 2024). "For example, dramatically elevated serum IL-10 in patients has been reported to play pro-inflammatory and immune-activating roles in COVID-19 pathogenesis, suggesting the unwanted effects of overly high circulating IL-10 concentrations." (PMID 39882328, 2024). "For instance, the study found that in COVID-19 patients, IL10 levels were positively correlated with metabolites involved in glycolysis and the pentose phosphate pathway, such as glucose, fructose, and ribose-5-phosphate." (PMID 39040605, 2024). "Recent studies have confirmed the critical role of IL-6 and IL-10 in predicting severe outcomes in hospitalized COVID-19 patients, further validating our findings." (PMID 39203987, 2024). "Here we examine the roles of the prototypic pro- and anti-inflammatory cytokines IFNγ and IL-10 using the rhesus macaque model of mild COVID-19." (PMID 38950078, 2024). "While previous studies have identified cytokines like IL-6, IL-10, and TNF-α as early severity predictors or associated with mortality in severe COVID-19, this study emphasizes the unique contribution of sTNFRI and sTNFRII levels." (PMID 39335653, 2024). "We did not evaluate the clinical severity of COVID-19 in this study, but in a previous study, we found that high IL-10 and IL-12 (P70) levels predicted worse clinical prognosis in hypertensive patients with COVID-19." (PMID 39685774, 2024). "Further, it has been confirmed that increased levels of IL-6 and IL-10 are independent and significant predictors of the severity and mortality of COVID-19." (PMID 38355623, 2024). "Using the REAC pathway analysis of differentially expressed genes in COVID-19-positive cases, we detected interleukin IL-2, IL-7, and IL-10 as well as IL-1, IL-4, IL-13, and IL-36." (PMID 38240884, 2024).
COVID-19 (continued). "Since the COVID-19 pandemic, many trials have found that the COVID-19 group had higher levels of IL-1, IL-6, and IL-10 than the control group." (PMID 38455049, 2024). "Conversely, IL-10 levels were significantly greater in both infected groups than in the control group, and this difference was more pronounced in COVID-19-only infected patients with a median concentration > 5 pg/mL." (PMID 39583156, 2024). "Studies have indicated that patients with severe COVID-19 exhibit elevated levels of pro-inflammatory cytokines (IL-6, tumor necrosis factor-α) and anti-inflammatory cytokines (IL-4, IL-10), along with decreased expression of CD4 and CD8 cells." (PMID 39040601, 2024). "The current study aims to investigate the predictive value and diagnostic potential of interleukins IL-10, IL-17A, IL-1β, IL-6, CXCL, and MCP for severe COVID-19 and COVID-19 mortality." (PMID 39062105, 2024). "COVID-19 induces uncontrolled inflammation, a so-called cytokine storm, including IL-6, IL-1b, IL-2, IL-10, TNF-α and monocyte chemoattractant protein (MCP-1)." (PMID 38732160, 2024). "We found a positive correlation between GDF-15 and TGF-β1 levels, with an inverse correlation between GDF-15 and IL-10 in COVID-19 patients." (PMID 38686386, 2024). "The significance of IL-10 in severe COVID-19 cases also prompts a reevaluation of therapeutic strategies aimed at modulating the immune response." (PMID 39203987, 2024). "Serum concentrations of IP-10, MCP-1, sTREM-1, and IL-10 levels can serve as biomarkers to predict adverse outcomes in COVID-19." (PMID 39654886, 2024). "In this study, we aimed to find out the association of genetic polymorphisms in TNF-α, IL-8, IL-10 and CXCR-2 genes with susceptibility to and mortality of COVID-19." (PMID 38544825, 2024). "A distinctive characteristic of the COVID-19 cytokine storm is the increased levels of IL-10 in critical patients." (PMID 37742314, 2024). "A number of cytokines signal through the JAK-STAT pathway, including IL-6, IL-2, IL-15, and IL-10, which are elevated in patients with COVID-19." (PMID 39599762, 2024). "Our results suggest that nVNS has an effect on inflammatory biomarkers in COVID-19, significantly increasing IL-10 levels." (PMID 39493183, 2024). "A study has found that inflammatory factors including IL-2, YKL40, IL-4, IL-6, IL-10, sCD40L, TNF-α, IL-1Ra, interferon-gamma (IFN-γ), and CRP, are associated with cognitive impairment in COVID-19 patients." (PMID 38012459, 2024). "Considering these findings, the coexistence of elevated NLR and cytokine levels, particularly IL-6 and IL-10, offers a window into the complex dynamics of the immune response to COVID-19." (PMID 39203987, 2024). "Research on IL-10 in the context of COVID-19 has thoroughly evaluated its role, revealing that higher levels of IL-10 correlate with more severe disease and have been shown to predict the progression to severe or critical disease." (PMID 38903511, 2024). "Regarding the anti-inflammatory cytokines, IL-1 receptor antagonists (IL-1Ra), IL-10, and IL-4 significantly increased across the different groups (mild, moderate, and severe) of COVID-19 patients." (PMID 38855114, 2024). "In summary, our study underscores the predictive value of the Neutrophil-to-Lymphocyte Ratio (NLR) and cytokine profiles, particularly IL-6 and IL-10, as markers in COVID-19." (PMID 39203987, 2024). "Thrush Candida albicans patients showed increased IL-8 (56.7 pg/mL) and IL-17 (101.1 pg/mL) concentrations, with the greatest concentration of IL-33 (200.5 pg/mL) in COVID-19, and a decrease in the level of IL-10 in patient groups compared with controls." (PMID 38747876, 2024). "Potential associations within COVID-19 group between heteroplasmic variant burden, along with the averaged REA values, and inflammatory mediators such as IL-6, IFN-α, TNF-α, and IL-10 were analyzed by Spearman rank correlation analysis." (PMID 38377022, 2024).
COVID-19 (continued). "The pathogenesis of COVID-19 involves intense inflammatory responses and encompasses a complex array of mediators, including IL-6, IL-8, and IL-10." (PMID 39654886, 2024). "Our study particularly focused on the concentration of anti-inflammatory cytokines (IL-4, IL-10) in the appendixes of children with COVID-19." (PMID 38397914, 2024). "The seven pro-inflammatory cytokines (IL-6, IL-8, IL-15, IL-18, IL-27, IFN-γ, and TNF-α) and two anti-inflammatory cytokines (IL-1RA and IL-10) were elevated in COVID-19 patients compared to healthy controls." (PMID 39408907, 2024). "Severe COVID-19 shows a distinct inflammatory phenotype with blunted anti-inflammatory responses, including IL-10 levels, in contrast to elevated pro-inflammatory cytokine levels." (PMID 38909235, 2024). "Most of the research focused attention on the first COVID-19 wave, in which high concentrations of IL-1β, tumor necrosis factor (TNF)-α, IL-6, IL-10, and interferon γ-induced protein (IP)-10 were observed in patients with severe forms of COVID-19." (PMID 39194742, 2024). "It is evident that increased circulating IL-10, IL-6, IFN-gamma-inducible protein 10 (IP-10), and monocyte chemoattractant protein-1 and -3 (MCP-1 and MCP-3) are significantly associated with COVID-19 severity." (PMID 39633683, 2024). "interleukin-6 (IL-6), IL-10, tumor necrosis factor (TNF)-α, IL-1β, IL-4, IL-8 and IL-17 are associated with increased severity as well as mortality in COVID-19 patients." (PMID 38544825, 2024). "IL-10 is upregulated early in disease progression, and along with IL-6, is a predictive biomarker for poor COVID-19 outcomes." (PMID 38950078, 2024). "For many of the most important mediators identified in predictive models of COVID-19 severity, concentrations appeared divergent early and throughout the course of symptoms, including IL-7, IL-10, lymphotoxin-α, TGF-α, VEGF-A, and MDC." (PMID 38368384, 2024). "Evaluate the state of the cytokine balance in the tissues of the appendixes of children of selected age groups with COVID-19 based on the levels of expression of pro-inflammatory (IL-1, IL-6) and anti-inflammatory (IL-4, IL-10) markers." (PMID 38397914, 2024). "Despite the limitations, the present study was able to shed some light on the association of cytokines, especially IL-6, IL-10, and IFN-γ, with COVID-19 disease severity." (PMID 38707035, 2024). "The elevation of pro-inflammatory cytokines and IL-10, an anti-inflammatory cytokine, unveils the dual dynamics of the immune response in the pathogenesis of COVID-19, suggesting the need for therapeutic strategies that effectively modulate this response." (PMID 39203987, 2024). "In this study, we found that IP-10, MCP-1, sTREM-1, and IL-10 have significant value in distinguishing COVID-19 patients with different clinical outcomes." (PMID 39654886, 2024). "In 2023, the authors further revealed that the excessive production of IL-10 and IL-6, coupled with reduced TGF-β levels, has been associated with cytokine storm-related fatalities in severe cases of SFTS and critically ill COVID-19 patients." (PMID 38389047, 2024). "IL-10 is a pivotal cytokine related to the regulation of inflammation in the development of COVID-19." (PMID 38710800, 2024). "Accordingly, several interleukins (e.g., IL-3, IL-6 or IL-10) have been identified as predictors of adverse events and higher mortality in COVID-19." (PMID 36769623, 2023). "IL-10, an anti-inflammatory cytokine, amplifies viral sepsis in severe COVID-19, probably through overactivation and proliferation." (PMID 37969879, 2023). "We found significantly higher serum levels of IL-6, IL-8, and IL-10 in patients with severe COVID-19 and in those with a fatal outcome." (PMID 37969879, 2023). "Our results showed significantly higher level of IL-1β, TNF-α, IL-12 and IL-10 in patients with stage IV of COVID-19 in comparison to milder forms of the disease." (PMID 36702907, 2023).
COVID-19 (continued). "Individuals affected by COVID-19 who need treatment in intensive care units usually have high levels of interleukin (IL)-2, IL-7, IL-10, tumor necrosis factor α (TNF-α), and other pro-inflammatory and also anti-inflammatory cytokines." (PMID 37408184, 2023). "It is also possible that exogenous IL-10 plays a useful therapeutic role in counteracting neurological symptoms observed in post-COVID-19." (PMID 37359549, 2023). "We assessed blood levels of Bregs expressing IL-35 and IL-10 surface markers in patients with different severities of COVID-19." (PMID 37833265, 2023). "Significantly higher levels of the anti-inflammatory cytokine IL-10 were found in COVID-19 patients, while the levels of IL-10 progressively increased, and those of testosterone progressively decreased with disease severity." (PMID 37896963, 2023). "IL-10 has been proposed as a potential therapeutic target for COVID-19, and IL-10 administration has been shown to reduce the inflammation and improve outcomes in animal models of COVID-19." (PMID 37649897, 2023). "Although previous studies have shown that patients with COVID-19 residing in high-altitude tend to have higher levels of inflammatory cytokines, particularly IL-6, IL-10 and TNF-α." (PMID 37264338, 2023). "Studies have shown that serum interleukin-10 levels are significantly higher in COVID-19 patients admitted to the intensive care units (ICUs) than in non-ICU patients." (PMID 38322760, 2023). "Consistently, we found the plasma levels of IL-5, IL-6, IL-8, IL-10 and IP-10 to be significantly higher in severe COVID-19 patients compared with control plasma." (PMID 37207201, 2023). "IL-10 is another cytokine which is significantly elevated during COVID-19 and correlates with poor clinical outcomes." (PMID 37371831, 2023). "Severe COVID-19 cases are characterized by an increase in pro-inflammatory cytokines plasma levels, especially interleukins IL-1β, IL-2, IL-6, IL-7, and IL-10 granulocyte-macrophage colony-stimulating factor (GM-CSF) and tumor necrosis factor-alpha (TNF-a)." (PMID 37445296, 2023). "In fact, there is another two papers, which pointed out down-regulation of IL-10 during COVID-19 infection and higher level of IL-10 was seen in recovered patients compared to severe COVID-19 patients." (PMID 36914565, 2023). "In the severe COVID-19 group, we observed a hyperinflammatory state, as judged by increased concentration of cytokines (IL-1α, IL-4, IL-6, IL-10 and IL-17A), chemokines (IP-10 and MIP-1β), and adhesion markers (E-selectin and ICAM-1)." (PMID 37441066, 2023). "Amongst those with acute COVID-19, eleven markers significantly differed across disease severity categories: IL-1β, IL-2, IL-6, IL-10, IL-18, IL-23, IL-33, TNF-α, IP-10, G-CSF and YKL-40." (PMID 37063871, 2023). "Convalescent COVID-19 children had elevated levels of IFNγ, IL-2, TNFα, IL-1α, IL-1β, IFNα, IFNβ, IL-6, IL-12, IL-17A, IL-10 and G-CSF in comparison to control children." (PMID 37013538, 2023). "An association between a high concentration of IL-10 with the fall and functional exhaustion of CD8+ and CD4+T cells has been found in COVID-19 patients, indicating that this cytokine plays a key role in SARS-CoV-2 pathogenesis." (PMID 37187739, 2023). "The cytokines TNF-α, IFN-γ, IL-6, IL-2, and IL-10 quantified in newborns of mothers with COVID-19 showed high levels of expression compared with the control group." (PMID 36979888, 2023). "The impaired IL-10 response in presence of high glucose can justify the increased frequency of mortality and severe complication in COVID-19 patients with diabetes or hyperglycemia and the better outcomes associated with improved glycemic control." (PMID 37359549, 2023). "A large increase in the proportion of IL-10-secreting regulatory T cells has been found in peripheral blood of patients with severe COVID-19, compared to those with mild-to-moderate cases and healthy individuals." (PMID 37359549, 2023).
COVID-19 (continued). "UCB mesenchymal cells reduce inflammation, including cytokine storms in COVID-19 patients, as indicated by decreased IL-4, IL-6, and IL-10 levels." (PMID 37763198, 2023). "Consistent with previous reports, IL-10 expression was significantly lower in Ascaris seronegative patients suggesting a role for this cytokine in the helminth-mediated mitigation of COVID-19 severity." (PMID 37622109, 2023). "In particular, PD1-treated M2 macrophages from AOSD and COVID-19 patients increased the production of IL-10 and enhanced homeostatic restoration through MIP-1β production." (PMID 37153620, 2023). "Several studies show that high IL-10 expression levels predict poor outcomes in patients with COVID-19 and appear to be a distinguishing feature of hyperinflammation during severe SARS-CoV-2 infection." (PMID 36882862, 2023). "In COVID-19 patients, IL-10 levels are reduced, leading to dysregulated immune responses and tissue damage." (PMID 37649897, 2023). "Elevation in IL-10 in COVID-19 patients can be justified as an effort to moderate hyper-inflammation and prevent tissue damage, but it fails to suppress the inflammation." (PMID 37283736, 2023). "Regarding IL-10, patients with COVID-19 had the highest serum levels, followed by bacterial pneumonia, and the lowest levels were seen in healthy controls." (PMID 38585537, 2023). "Post-COVID-19 exhibited lower levels of serum IL-6 (p adj <0.01), whereas it showed higher serum IL-10, triglyceride, leptin, IgG, ACE activity, TNFRSF1A, and PGE2 (p adj <0.05) levels compared with controls." (PMID 37753077, 2023). "There were statistically significant differences in the levels of IL-10 cytokines among HCWs with severe COVID-19 in different age groups." (PMID 36908474, 2023). "Cardiovascular and respiratory symptoms are other persistent clinical signs, among those commonly affecting post-COVID-19 patients, which can be positively influenced by IL-10." (PMID 37359549, 2023). "This evidence suggests an analgesic function for IL-10 in the context of post-COVID-19 and proposes that this cytokine can significantly improve the patient’s quality of life, resolving the chronic pain debilitating condition." (PMID 37359549, 2023). "The almost unchanged ratio between IL-10 and proinflammatory cytokines during COVID-19 progression points on similar dynamics of all cytokine’s growth." (PMID 36702907, 2023). "Patients with severe COVID-19 showed significant increases in cytokines, including IL-2, IL-7, IL-10, GSCF, IP10, MCP-1, MIP1A and TNF-α, with the characteristics of a cytokine storm." (PMID 37112613, 2023). "Even though IL-10 has anti-inflammatory properties, some studies show a pro-inflammatory effect in COVID-19 patients." (PMID 36901868, 2023). "In COVID-19, the level of interleukin 10 is elevated and should act as an immunosuppressant, quite contrary to early pathological IL-10 elevation, which contributes to COVID-19 severity." (PMID 37762549, 2023). "The antiviral IFN-α and proinflammatory TNF, IL-6, IL-8, IL-17, IL-33, and IFN-γ were elevated in COVID-19 patients at both time points, while IL-10 and IL-1β were increased at admission and one week later, respectively." (PMID 37174682, 2023). "(C) Relative expression of IFNγ, IL-17A, TGFβ, and IL-10 genes in peripheral blood CD3+ CD4+ cells from COVID-19 patients (moderate or severe) and healthy control (HC)." (PMID 37523305, 2023). "Distinct serum cytokine profiles are observed in association with COVID-19 severity, with the most severe patients having elevated levels of TNF-α, IL-6, IL-8, and IL-10." (PMID 37111341, 2023). "Increased cytokine levels (IL-6, IL-10, and TNF-α) and decreased IFN-γ expression in CD4+ T cells have been associated with severe COVID-19 in adults." (PMID 37602239, 2023). "Transcripts of genes encoding 6 biomarkers, IL-1β, IL-6, IL-10, C-reactive protein, IDO1 and ACE2, were measured by RT‒qPCR in saliva samples of patients and COVID-19-free individuals." (PMID 37715121, 2023).